IL4 (interleukin 4)
Diseases named in the same sentence as IL4 in open-access papers (continued):
Sharing a sentence is not in itself a finding about the gene and the disease.
colitis (236 papers, 2008 to 2026). Inflammation of the colon. "IL-4 modulation by iTcES in colitis and the recently described benefits of IL-4-stimulated (M2) macrophage transfer in colitis and colitis-associated colon cancer (CAC) highlight the therapeutic potential of M2 macrophages." (PMID 40576745, 2025). "Here, our data suggest that the deficiency of Mcpt-4 triggered a stronger Th2 response in colitis as manifested by increased levels of IL-4, IL-5, IL-10, and IL-13, whereas IL-10 is also generally known as an anti-inflammatory cytokine." (PMID 40697820, 2025). "Dextran sulfate sodium-induced colitis in mice was hampered by IL-4 deficiency in a mouse experiment." (PMID 39451595, 2024). "Further studies have shown that Hpb colonization protects mice from TNBS-induced colitis while upregulating the Th2-associated cytokines, IL4, IL5, and IL13, and the regulatory cytokine, IL10." (PMID 37189818, 2023). "Perinatal exposure to TiO2 also exacerbated the colitis, as evidenced by a reduced colon length associated with increased colonic mRNA expression and protein levels of IL-1β, IL-4, IL-12, IL-13, IFNγ and TNF-α." (PMID 37996842, 2023). "In the gut, elevated IL-4 has been previously associated with enhanced serum IgE and colitis in WASp-deficient mice." (PMID 35265075, 2022). "Since macrophages activated by TH2-type cytokines share some characteristics of tumor-associated macrophages (TAMs) we evaluated the putative tumorigenic property of M(IL4) transfer in a model of colitis-associated CRC." (PMID 34691050, 2021). "The reduced colitis severity in these mice was associated with increased expression of IL4 and distinct activation pattern of stromal cells derived from transplanted peripheral lymph nodes." (PMID 33664727, 2020). "IL-4 and IL-13 have also been reported to play critical pathogenic roles in animal models of colitis." (PMID 33192516, 2020). "Our own studies have demonstrated that CD4+ T cells and B cells deficient in the IL-4/IL-13 common receptor IL-4Rα are protected from oxazolone-induced colitis." (PMID 32410852, 2020). "IL-4 deficient mice have been reported to show amelioration of DSS-induced colitis, suggesting the pathogenic role of IL-4 in DSS-induced colitis model." (PMID 33192516, 2020). "Th1 and Th2 cytokines, such as interferon-γ (IFN-γ), interleukin-4 (IL-4), and interleukin-5 (IL-5), are closely associated with the pathogenesis of colitis induced by DSS." (PMID 29888292, 2018). "Type-2 gut inflammation is not driven by IL-12 and IFN-γ, but is thought to be caused by elevated levels of IL-4, IL-5, and IL-13 and studies have shown a delay in the onset of colitis when IL-4 is blocked by a neutralizing anti-IL-4 antibody." (PMID 22539101, 2012). "The colitis was exacerbated in these animals, as evidenced by a reduced colon length associated with increased colonic mRNA expression and protein levels of IL-1β, IL-4, IL-12, IL-13, IFNγ and TNF-α." (PMID 37996842, 2023). "Although the detailed mechanism remains unclear, IL-4-deficiency impaired dextran sulfate sodium-induced colitis." (PMID 36362231, 2022). "Since IgG2- and IgG3-producing cells were increased in IL-4-deficient mice, these conditions may have a beneficial effect on colitis." (PMID 36362231, 2022). "Indeed, IL-4 deficiency can prevent the development of colitis in IL-10 knock out mice, which spontaneously develop colitis." (PMID 34737752, 2021). "However, Il4-/-Il10-/- double deficient mice showed decreased colitis induction after DSS treatment indicating that IL4 alone is not sufficient to reduce chronic colitis severity." (PMID 33664727, 2020). "Beyond that, our study supported a new relationship among IL-4, CD103+ DCs, and epithelial cells in the pathogenesis of IBDs: in the initial phase of colitis, abnormal Th2 type immune response causes an increased IL-4 expression that leads to loss of tolerogenic CD103+ DC and Treg cells dysfunction." (PMID 28316599, 2017).
colitis (continued). "Furthermore, in this study, the therapeutic potential of IL-4 in TNBS-induced colitis was associated with inhibition of the induction of nitric oxide (NO) expression and reduction of its synthesis." (PMID 27576902, 2016). "Several studies have suggested that overexpression of GATA-3 in T cells could markedly aggravate the severity of DSS-induced colitis in mice and that IL-4-deficient mice develop less severe DSS-induced colitis than WT mice do." (PMID 27110068, 2016). "Moreover, STAT6 critically mediates the pro-inflammatory properties of the Th2 signature cytokine IL-4 in murine colitis, causes IL-4-dependent inhibition of Foxp3 and, thus, reduced Treg induction." (PMID 26938566, 2016). "The results showed that allergen-related colitis was induced in mice as shown by heavy infiltration of inflammatory cells in the colon mucosa, loss of body weight of mice, increases in myeloperoxidase, tumor necrosis factor-α, interleukin-4, OVA-specific IgE in the colon tissue." (PMID 27604348, 2016). "Modulating the Treg/Th2 response by decreasing proinflammatory cytokines such as TNFα, IL-6, IL-1β, IL-18, IL-22, IL-9 and increasing anti-inflammatory cytokines IL-10 and IL-4 in mice colitis model." (PMID 41208998, 2025). "iTcES treatment elevated IL-4 production, favoring an M2 macrophage profile in the peritoneum and colon, thereby establishing an anti-inflammatory microenvironment that modulates colitis." (PMID 40576745, 2025). "IL4 promotes the healing processes accomplished by macrophages and has an alleviating effect upon patients with colitis." (PMID 40002872, 2025). "A study with Citrobacter rodentium, a murine model for pathogenic E. coli infection, showed the beneficial effect of IL4 treatments for mucosal healing by affecting mucus production, pathogen adhesion, and colitis." (PMID 40302745, 2025). "Another study showed the beneficial effects of AdV-mediated IL-4 overexpression in a rat TNBS colitis model whereas IL-4 gene transfer to the healthy intestine triggers inflammation." (PMID 41463087, 2025). "We next investigated if the maintenance of suppressive capacity of IL-4 induced ex-iTreg cells was evident in an in vivo adoptive T cell transfer model of colitis." (PMID 40568113, 2025). "AhR activation has been linked to the alleviation of colitis by reducing inflammatory cytokines like IL‐1β, IL‐6, and TNF‐α, while enhancing anti‐inflammatory cytokines, such as IL‐4, IL‐10, and IL‐22, and strengthening the intestinal epithelial barrier." (PMID 39836604, 2025). "DSS-induced colitis significantly elevated pro-inflammatory mediators (IL-17, IL-23; both p < 0.05 vs. NC) while suppressing the anti-inflammatory cytokine IL-4 (p < 0.001)." (PMID 40725052, 2025). "Th2 cells, in contrast, are characterized by their secretion of interleukin-4 (IL-4), interleukin-5 (IL-5), and interleukin-13 (IL-13), which can contribute to the transition from colitis to cancer." (PMID 39575712, 2024). "This is supported by an independent study showing that administration of BMDM stimulated with the Th2 cytokine IL-4 improved the severity of experimental colitis in mice." (PMID 38714733, 2024). "Perilla seed oil, rich in α-linolenic acid, reduces colitis by suppressing inflammatory markers including interleukin-1 (IL-1), interleukin-2 (IL-2), interleukin-4 (IL-4), interleukin-5 (IL-5), interleukin-6 (IL-6), and interleukin-10 (IL-10)." (PMID 39022021, 2024). "When compared to control colitis animals, the expressions of inflammatory markers such as IL-1β, IL-4, IL-6, and Cxcl2 were significantly lower in mice receiving IAA treatment." (PMID 39068517, 2024). "A population of T helper cells co-expressing IL-9 and IL-4 was already reported in the literature, indicating that this population can activate eosinophils in colitis and is involved in the effector function of T helper cells in this disease." (PMID 37676302, 2023).
colitis (continued). "We also subjected VB1-deficient diet-fed mice to trinitrobenzene sulphonic acid (TNBS)-induced colitis, in which IL-4 is reported to contribute to the amelioration of disease." (PMID 37163450, 2023). "The closely correlated pro-inflammatory cytokines in lipid metabolism are TNF-a, IL-17a, IL-4, and IL-6, and these molecules promote colitis progression." (PMID 37569708, 2023). "In experimental mouse models of colitis, IL-4 and IL-13 production contributes to disease pathogenesis with levels increasing progressively from pre- to early- to late-stage disease." (PMID 36749569, 2023). "Exogenous administration of IL-1β reduces the expression of colonic Th2 cytokines IL-4 and IL-13 and improves colitis, while exogenous IL-18 also reduces the severity of colitis but does not affect the expression of Th2 cytokines." (PMID 37370025, 2023). "In order to promote the balance of Th1/Th2 cells in rats with colitis, WMW increased IFN-γ and decreased IL-4 to address the immunological imbalance in colitis." (PMID 37836654, 2023). "Nevertheless, no IL-10 activation was observed, which functions as an anti-inflammatory mediator to downregulate the expression of Th1-derived cytokines, and promote IL-4, classified as Th2-derived cytokines to reduce colitis." (PMID 37509556, 2023). "For example, adoptive transfer of in vitro-derived IL-4/IL-13-stimulated M2a Mφ into mice depleted of resident Mφ resulted in reduced dinitrobenzene sulfonic acid (DNBS)-induced colitis symptoms in mice." (PMID 37768050, 2023). "By using IL-4Rα−/− mice, our study has provided the first direct experimental evidence for the role of IL-4/13 signaling in the repair of DSS-induced colitis in WT mice." (PMID 37768050, 2023). "For T. spiralis, cystatin can block the Th1-type immune response in TNBS-induced colitis by boosting the production of IL-4 and Treg cells." (PMID 38152266, 2023). "The murine model by Leung showed that bone marrow-derived macrophages treated with IL-4 were shown to block colitis." (PMID 38137450, 2023). "L. bulgaricus and S. thermophilus in yogurt alleviated the symptoms of colitis in mice and induced IL-2 and IL-4 production in the lymph nodes and spleen, resulting in modulated helper T cells." (PMID 36986118, 2023). "In Peter’s experiment, the presence of IL-33 exacerbated DSS-induced colitis in mice, while genetically knocking out IL-4 abolished this effect, suggesting that IL-33 primarily worsens colitis through the Th2 immune response." (PMID 37686309, 2023). "The expression of CRP, ESR, FC, interleukin-6(IL-6), IL-8 and IL-10 were different between the two groups, and except for IL-4 and IL-12P70, the expression of inflammatory markers was higher in extensive colitis." (PMID 37457023, 2023). "For example, human IL‐4‐induced regulatory macrophages (M2‐like) promoted epithelial tissue healing in a mouse colitis model." (PMID 36541165, 2023). "Exogenous IL-4 treatment had controversial effects on clinical remission and mucosal healing in colitis models." (PMID 38058517, 2023). "Here, we identified that A. muciniphila indeed increased the level of IL-4, resulting in M2 macrophage polarization in the colitis locus." (PMID 36599931, 2023). "Studies have shown that the type 2 cytokines IL-4 and IL-13 play a major role in macrophage-mediated epithelial wound healing and that they promote colitis alleviation." (PMID 37189566, 2023). "Despite almost undetectable IL-4 mRNA expression in the intestinal mucosa of patients with CD and UC, the administration of anti-IL-4 led to a significant improvement in oxazolone colitis." (PMID 38137450, 2023). "Colitis mice treated with Trichinella spiralis extracellular vesicles (Ts-Evs) showed a significant increase in the CD4+IL-4+ cell populations compared to the TNBS group, which was associated with ameliorating colitis by the expansion of Th2 cells." (PMID 35741032, 2022).
colitis (continued). "DSS-induced colitis has been shown to induce T-helper cell 2 (Th2) immune responses in the gastrointestinal tract, with IL-4 and IL-13 being identified as important effector cytokines." (PMID 36558966, 2022). "As for anti-inflammatory cytokines, LCA, DCA, and HDCA did not alter the mRNA levels of Il10 while DCA and HDCA increased the mRNA levels of Il4 in colitis mice." (PMID 36050867, 2022). "Another interesting study in primates demonstrated that the experimental administration of Trichuris trichiura can ameliorate colitis by both induction the colonic CD4+ T cells producing IL-4 and modulation of microbial populations." (PMID 35435504, 2022). "Administration of T. halophilus in mice with DSS-induced colitis upregulated the frequencies of IL-4+ cells in CD4+ T cells (51.27 ± 4.58% vs. 23.96 ± 9.40%, p < 0.001) and in CD8+ T cells (37.27 ± 90% vs. 16.93 ± 6.88%, p < 0.001)." (PMID 35741032, 2022). "IL-4+ cells in CD4+ T cells from DSS-induced colitis mice were significantly reduced compared to controls (23.96 ± 9.40% vs. 43.38 ± 2.55%, p < 0.01)." (PMID 35741032, 2022). "After administration of SI, IL-4, IL-5, and IL-13 levels were significantly reduced in the colonic mucosa of SI-treated mice compared to those in the colitis group (p < 0.05)." (PMID 36359214, 2022). "Colonic tissues from DSS-induced colitis mice with Blastocystis ST4 colonization demonstrated increased expression of Th2 (IL-4, IL-5, and IL-13) cytokines relative to control mice." (PMID 35435504, 2022). "In this context, the serum levels of IL-4, IL-1b, and TNFαwere examined, and we found that these increased cytokines in colitis mice were suppressed by CYN and mesalamine, as evidenced by ELISA experiments." (PMID 36278202, 2022). "The qRT-PCR results showed that IL-4, IL-5, and IL-13 levels were significantly higher in the intestinal mucosa of colitis-induced mice than those in the control group (p < 0.05)." (PMID 36359214, 2022). "D5R signaling suppressed the development of experimental colitis by regulating the balance of colonic M1/M2 macrophages, specifically the inhibition of M1 and the promotion of the IL-4/IL-13-triggered M2 macrophage polarization, respectively." (PMID 34884737, 2021). "A study on human IL4-treated regulatory macrophages also revealed that IL4 treatment promoted epithelial wound healing and reduced the severity of colitis in mouse models." (PMID 35008767, 2021). "In vivo, IL-4 production by eosinophils has been shown to promote colitis in both the chemically induced dextran sodium sulphate (DSS), as well as in the T cell transfer model." (PMID 34737752, 2021). "Mice lacking IL-4Rα did not develop disease in this model, further indicating a potential role for IL-4 in the development of colitis and inflammation." (PMID 34737752, 2021). "Yeti iNKT cells displayed a pronounced anti-inflammatory (IL4- or IL9-producing) phenotype during colitis." (PMID 33513946, 2021). "Overall, these findings indicate that M(IL4) transfer protects against colitis induced by C. rodentium-infection." (PMID 34691050, 2021). "The anti-colitic effect of the M(IL4)s were confirmed in the di-nitrobenzene sulphonic acid model of colitis and the lumen-to-blood movement of 4kDa FITC-dextran and bacterial translocation to the spleen and liver was also improved by M(IL4) treatment." (PMID 34691050, 2021). "Collectively, these results confirm the protective role of M(IL4) in the DNBS-model of acute colitis." (PMID 34691050, 2021). "Recently, an IL-4/IL-13 dual antagonist was developed and evaluated in a murine model of oxazolone-induced colitis, where it showed to ameliorate overall disease activity." (PMID 34737752, 2021). "Our data suggests a redundant role for IL-4/IL-13 signalling on macrophages in acute oxazolone-induced colitis." (PMID 32410852, 2020).
colitis (continued). "In OXZ colitis, IL-4 is the initial cytokine produced by oxazolone colitis, but IL-4 is soon replaced by the production of IL-13, which can activate epithelial cells to secrete mucus and fluid." (PMID 33237174, 2020). "As with Th1-type cytokines, IL-4 is also known to be highly immunogenic and is commonly elevated in colitis." (PMID 32992618, 2020). "Promoting the generation of some anti-inflammatory cytokines (such as IL-4 and IL-10) has been shown to attenuate colitis in vivo." (PMID 33312339, 2020). "Sinapic acid treatment increased the serum levels of IL-4 and IL-10 in colitis mice and promoted the mRNA expression of these anti-inflammatory cytokines in the colons of colitis mice." (PMID 33312339, 2020). "As colitis in Il10-/- mice is dependent on Th1 and Th17 immune responses, increased expression of IL4 can act as a negative regulator of inflammation." (PMID 33664727, 2020). "CD4+ T cell subsets in the colitis tissues were identified using qPCR—T-bet and Ifn-γ for Th1, Gata-3 and Il-4 for Th2, Rorγt and Il-17 for Th17, and Foxp3 and Il-10 for Treg subsets." (PMID 33092149, 2020). "SSP and 5-ASA significantly reduced IL-1β, IL-4, IL-9, and IL-17A concentrations in the colitis mice, followed by lower expression of the CD11c+CD103+E-cadherin+ and CD11c+CD103+TNF-α+ cells." (PMID 32754049, 2020). "In this study, oxazolone colitis was treatable with adoptively transferred IL-4-stimulated cryopreserved macrophages, likely alternatively activated macrophages." (PMID 32410852, 2020). "To address the role that IL-4/IL-13 signalling plays on macrophages in oxazolone-induced colitis, we used the macrophage/neutrophil-specific IL-4Rα-deficient mouse strain (LysMcreIL-4Rα-/lox)." (PMID 32410852, 2020). "Combined, our data suggests that IL-4/IL-13 signalling on intestinal epithelial cells, smooth muscle cells, macrophages, and neutrophils plays a redundant role in oxazolone colitis." (PMID 32410852, 2020). "The mRNA expression of Il-4 was significantly lower in IL-4Rα-/- colitis mice than in WT colitis mice." (PMID 33192516, 2020). "In oxazolone-induced colitis, the administration of anti-IL-4 led to the amelioration of disease, suggesting a detrimental role of this cytokine in experimental intestinal inflammation." (PMID 33371444, 2020). "DSS treatment significantly decreased the levels of IL-4 and IL-10 in the serum of the colitis mice." (PMID 33312339, 2020). "To understand the mechanism that underlies the alleviation of DSS-induced colitis in mice after treatment with EPS-1, we examined the levels of Th1 pro-inflammatory (TNF-α, IL-6, and IFN-γ) and anti-inflammatory (IL-4 and IL-10) in colon tissues." (PMID 30708992, 2019). "In vivo IL-4 administration initiated 10 days after infection increased mucus thickness and quality and decreased colitis and pathogen contact with the epithelium." (PMID 30665337, 2019). "The number of regulatory T (Treg) cells in the spleens of mice with colitis and levels of IL-4 both increased following treatment with M2b macrophage exosomes." (PMID 31749791, 2019). "Studies have shown that OXZ-induced colitis is an IL-4-driven model and that IL-4 production increases during disease development." (PMID 31878303, 2019). "In a mouse model of T cell-induced colitis, GM-CSF increased the production of IL-4, IL-10, and IL-13 and decreased the production of interferon gamma (IFN-γ) in lamina propria mononuclear cells." (PMID 29703251, 2018). "In vivo, colonic mucosa of children with colitis had significantly increased expression of IL-4 in CD8+ T cells compared with controls." (PMID 29922282, 2018). "Such cells co-expressing activated caspase-3 and IL-4 can be identified in the mucosa of children with colitis." (PMID 29922282, 2018). "In fact, we found that IL-4 expression by colonic CD8+ IELs was significantly increased in children with colitis compared with control subjects." (PMID 29922282, 2018).